ANGPT1 (angiopoietin 1)
Diseases named in the same sentence as ANGPT1 in open-access papers (continued):
Sharing a sentence is not in itself a finding about the gene and the disease.
mastocytosis (1 paper, 2021). A clonal myeloproliferative neoplasm characterized by the proliferation and accumulation of neoplastic mast cells in one or multiple organs or organ systems. "Serum concentrations of tryptase, VEGF-A and ANGPT1 are increased in indolent and advanced mastocytosis compared to healthy controls." (PMID 33687603, 2021). "The aim of this paper was to evaluate the serum concentrations of VEGF-A, VEGF-C, VEGF-D, ANGPT1 and ANGPT2 in patients with different variants of mastocytosis and the expression of angiogenic and lymphangiogenic factors in human MC lines with or without D816V mutation." (PMID 33687603, 2021). "It is possible to speculate that the increase in circulating ANGPT1 in all patients with mastocytosis might represent a protective factor in counterbalancing the vasopermeability effect of VEGF-A and ANGPT2." (PMID 33687603, 2021). "Interestingly, both ANGPT2, which increases vascular permeability, and its antagonist ANGPT1 were increased in mastocytosis patients compared to HC [ANGPT1: (1,538 ± 2,136) vs (39.93 ± 45.60 pg/mL)] [ANGPT2: (1,492 ± 976) vs (1,085 ± 607) pg/mL]." (PMID 33687603, 2021). "Interestingly, the serum concentration of ANGPT1, which is mainly produced by pericytes and inhibits endothelial cell permeability, is increased in all mastocytosis patients." (PMID 33687603, 2021). "Serum concentrations of VEGF-A, VEGF-C, ANGPT1 and ANGPT2 are increased in patients with mastocytosis compared to healthy controls." (PMID 33687603, 2021). "VEGF-A, ANGPT1, ANGPT2 and VEGF-C concentrations were higher in mastocytosis patients compared to controls." (PMID 33687603, 2021). "Serum concentrations of VEGF-A, VEGF-C, VEGF-D, ANGPT1 and ANGPT2 were determined in 64 mastocytosis patients and 64 healthy controls." (PMID 33687603, 2021). "ANGPT2, which is released mainly by endothelial cells, and ANGPT1/ANGPT2 ratio, an index of vascular permeability, are increased only in advanced mastocytosis." (PMID 33687603, 2021). "A triplex experimental analysis was used to verify whether enhanced levels of VEGF-A, ANGPT1, ANGPT2 and VEGF-C were correlated with mastocytosis severity." (PMID 33687603, 2021). "However, the lack of correlation between tryptase and both VEGF-A and ANGPT1 might indicate that alternative sources of the two latter mediators are involved in mastocytosis." (PMID 33687603, 2021).
meningioma (1 paper, 2021). A generally slow growing tumor attached to the dura mater. "ANGPT-1 as well as active form of TGF-β1 demonstrated difference between healthy control and meningioma group." (PMID 34162919, 2021).
onchocerciasis (1 paper, 2009). Onchocerciasis is a form of filariasis, caused by the parasitic worm Onchocerca volvulus, transmitted by the black fly. "The neovascularisation was associated with a particular pattern of angio/lymphangiogenic factors in nodules of onchocerciasis patients, characterized by the expression of CXCL12, CXCR4, VEGF-C, Angiopoietin-1 and Angiopoietin-2." (PMID 20011036, 2009).
Optic neuropathy (1 paper, 2021). "Mouse mutants with conditional deletion of the Angiopoietin 1 and 2 (Angpt1/2) ligands that bind to the TIE receptors develop ocular enlargement and optic neuropathy, in addition to complete absence of Schlemm's canal, a modified lymphatic that drains aqueous humor from the eye." (PMID 33975254, 2021).
osteoporosis (1 paper, 2016). A condition of reduced bone mass, with decreased cortical thickness and a decrease in the number and size of the trabeculae of cancellous bone (but normal chemical composition), resulting in increased fracture incidence. "SPP1 (secreted phosphoprotein 1), COL1A1 (collagen type I α 1 chain), NT5E (5′-nucleotidase ecto), HTRA1 (HtrA serine peptidase 1) and ANGPT1 (angiopoietin 1) and their signalling pathways involving osteoporosis in CD patients are identified." (PMID 27690016, 2016). "SPP1 signalling and COL1A1 signalling in osteoporosis were previously reported; and NT5E, HTRA1 and ANGPT1 signalling pathways reported here require further confirmation." (PMID 27690016, 2016). "Secreted phosphoprotein 1 (SPP1), collagen type I α 1 chain (COL1A1), 5′-nucleotidase ecto (NT5E), HtrA serine peptidase 1 (HTRA1) and angiopoietin 1 (ANGPT1) and their signalling pathways are shown to be involved in osteoporosis in CD patients." (PMID 27690016, 2016). "Although the molecluar mechanism of NT5E, HTRA1 and ANGPT1 in osteoporosis has not been studied yet, the signaling pathways regulated by them are closely related to the signal pathways of bone development and formation." (PMID 27690016, 2016).
ovarian failure (1 paper, 2020). "ANGPT1 in the ANGPTLs family can affect the production of steroid hormones, reduce premature ovarian failure, and promote the proliferation of mouse sinusiform follicles." (PMID 32988397, 2020).
parasitic infections (1 paper, 2017). "Expression of genes involved in endothelial activation such as PECAM1, and angiogenesis such as VEGF, angiopoietin 1 and 2 are commonly involved in the pathogenesis of parasitic infections." (PMID 29190292, 2017).
periapical granuloma (1 paper, 2022). Chronic nonsuppurative inflammation of periapical tissue resulting from irritation following pulp disease or endodontic treatment. "In this study, we found up-regulation of ANGPT1 in the non-healing group, which may be associated with high vascularity as observed clinically in the periapical granuloma." (PMID 35970906, 2022).
Pleural effusion (1 paper, 2020). The presence of an excessive amount of fluid in the pleural cavity. "In order to determine the prognostic value of pleural effusion derived Angiopoietin-1, HGF, MMP-7, Osteopontin, TIMP-1, Galectin, Mesothelin, NRG1-b1, SDC-1 and VEGF, we divided patients in two groups depending on the established cut-off value for all analytes." (PMID 32731396, 2020). "Moreover, there is a negative correlation between Mesothelin and shed SDC-1 and positive correlation between VEGF, Angiopoietin-1 and shed SDC-1 level in the pleural effusion from malignant cases." (PMID 32731396, 2020).
prostate tumor (1 paper, 2012). "Also angiopoietin 1 and its receptor Tie-2 were found in both prostate tumor cells and capillaries, where they can induce sprouting angiogenesis." (PMID 23009291, 2012).
pulmonary edema (1 paper, 2025). Accumulation of fluid in the lung tissues causing disturbance of the gas exchange that may lead to respiratory failure. "Later, Interleukin-2 (IL-2) and angiopoietin-1 (Ang-1) were sequentially introduced into this model to replicate the pathophysiology of pulmonary edema." (PMID 40528968, 2025).
radiation-induced gastrointestinal syndrome (1 paper, 2019). "Moreover, the prevention of endothelial cell damage by growth factors such as VEGF, bFGF, and ANGPT-1 variants inhibit crypt cell damage, organ failure, and death during radiation-induced gastrointestinal syndrome." (PMID 30841658, 2019).
renal carcinoma (1 paper, 2012). A carcinoma arising from the epithelium of the renal parenchyma or the renal pelvis. "sFRP-2 activated the Wnt pathway and promoted renal cancer growth whereas sFRP-3 expression induced the MMP-3 and ANGPT1 genes in renal cancer and thus contributed to the invasive capability of RCC." (PMID 22325146, 2012).
renal dysfunction (1 paper, 2025). "Notably, patients with CKD or renal dysfunction display changes in corresponding genes, such as a loss of the endothelial marker CDH5, an increase in ANGPT2 and PDGFB, and a reduction in ANGPT1." (PMID 40952790, 2025).
retinal degeneration (1 paper, 2018). Degeneration of the retina. "In hyperoxia, which in short-term promotes astrocyte differentiation, in long-term causes retinal degeneration and paradoxically can cause hypoxia by blocking vascular development in the retina, Angpt1 mRNA expression was decreased while Angpt2 and Angpt4 mRNA levels increased." (PMID 30444491, 2018).
rosacea (1 paper, 2025). A chronic erythematous skin disorder that affects the face. "In this study we explored the expression of Angiopoietin 1, Angiopoietin 2, and Tie2 by immunohistochemistry in rosacea lesions." (PMID 41562711, 2025).
skin melanoma (1 paper, 2021). "ANGPT2 gene expression is significantly higher (P < 0.01) in skin melanoma compared to normal skin, whereas expression of ANGPT1, PDGFA, FGF2, and VEGF‐A is not significantly different." (PMID 34102002, 2021).
teratoma (1 paper, 2016). A non-seminomatous germ cell tumor characterized by the presence of various tissues which correspond to the different germinal layers (endoderm, mesoderm, and ectoderm). "We were able to detect two proteins, enolase-2 and angiopoietin-1, which showed consistent concentration increases over time in three out of four animals with confirmed teratomas." (PMID 26777057, 2016).
uveal melanoma (1 paper, 2021). A melanoma derived from melanocytes of the uveal tract. "We hypothesize that proangiogenic factors such as angiopoietin-1 (ANG-1) and angiopoietin-2 (ANG-2), two targetable cytokines, may play a role in tumor development in uveal melanoma." (PMID 34439141, 2021).
tumor (195 papers, 2002 to 2025). "Angiopoietin-1, among factors implicated in tumor angiogenesis, has been linked to HCC progression and has shown superior performance to AFP in predicting overall survival." (PMID 39286634, 2024). "Multiple studies have confirmed the increased serum levels of VEGF and Angpt1 in placental trophoblastic disease and tumor patients, indicating the association of pro-angiogenesis factors with these diseases." (PMID 36846460, 2023). "ANGPT1 encodes a secreted glycoprotein, which plays important role in vascular development and angiogenesis, thereby promoting the tumor dedifferentiation and development of HCC." (PMID 34252885, 2021). "Due to the role of TIE2 and ANGPT1 in tumor-associated angiogenesis, TIE2 is a target for anti-angiogenic therapies, and anti-TIE2 agents have been developed." (PMID 32260072, 2020). "In the current work, the presence of angiopoietin-1 in the TIF was associated with an enhanced incidence of local tumor recurrence (p = 0.007)." (PMID 31830991, 2019). "ANGPT1 encodes a secreted glycoprotein that belongs to the angiopoietin family and plays an important role in tumor vascularization as an agonist of angiogenic receptor TEK." (PMID 29113349, 2017). "This “window” is associated with the increase of pericyte coverage and angiopoietin-1 (Ang1) expression and thinning of basement membranes, resulting in enhanced tumor oxygenation." (PMID 27446811, 2016). "Following estrogen depletion, the BM niche cells produced angiopoietin-2 (ANGPT2), which destabilized niche endothelium by interfering ANGPT1/Tie2 signaling, and promoted ER+ tumor cell survival under estrogen deficiency via cell surface integrin &1." (PMID 27353038, 2016). "We report here that angiopoietin-1 overexpression resulted in stabilization of tumour edge-associated blood vessels, as it prevented vessel dilation and dissociation of smooth muscle cells from existing vessels." (PMID 11870550, 2002). "In addition, increased circulating platelets and neutrophils produce vascular endothelial growth factor, angiopoietin-1, and fibroblast growth factor-2, causing tumor angiogenesis." (PMID 29029493, 2017). "Therefore, we conclude that deregulated angiopoietins expression can be linked with a significantly more pronounced biological aggressiveness of the tumour tissue; in particular, the expression of ANGPT1 was associated with lymphatic metastasis." (PMID 26044849, 2015). "The up-regulation of ANGPT1 in many cancers suggests this gene is strongly associated with tumour malignancy, and this could mean that ANGPT1 rs2445365 affects the activity of this protein and that activation of angiopoietin-1/Tek signalling in the vasculature could induce metastasis." (PMID 33573134, 2021). "High levels of ANGPT2 compared to ANGPT1 positively correlate with tumor vascularity, tumor growth, and poorer prognosis." (PMID 39866233, 2025). "Platelets release proangiogenic factors, such as vascular endothelial growth factor (VEGF) and angiopoietin-1, which are critical for neovascularization and tumor progression." (PMID 40647360, 2025). "Nevertheless, ANGPT-1 had a significantly lower expression pattern in tumor samples than normal colon tissue (P-value = 0.003)." (PMID 38719941, 2024). "Nevertheless, ANGPT-1 had a significantly lower expression in tumor samples than in normal colon tissue (P-value < 0.01)." (PMID 38719941, 2024). "After VEGF blockade, expression level of ANGPT1 increased in a narrow therapeutic window during tumor oxygenation, while ANGPT2 induced vascular remodeling and sprouting under hypoxic TME at Bev resistance." (PMID 38619734, 2024). "In vitro experiments revealed that these cells migrate to PC sites in response to high levels of pro-angiogenic factors such as VEGF and Angiopoietin-1 secreted by tumor cells." (PMID 39020414, 2024).
tumor (continued). "In summary, this study reveals differential activation of salvage angiogenic pathways in surgical specimens, with FGF2, EphA2, and PLGF upregulated in tumor vessels, while ANGPT1 and ANGPT2 were downregulated and upregulated, respectively." (PMID 38619734, 2024). "In contrast to the pro-angiogenic effects of TGF-β in tumor cells, we observed that loss of TGF-β signaling in ECs led to increased expression of VEGFA and angiopoietin-1, suggesting distinct mechanisms within the endothelial compartment." (PMID 39758992, 2024). "Mast cells are recruited to the TME by cytokines produced by tumor cells such as vascular endothelial growth factors (VEGFs), angiogenic hormone (ANGPT1), CCL2, and CXCL12 chemokines." (PMID 37161430, 2023). "HIFs, with other pathways in the tumours microenvironment, trigger the expression of angiogenesis-promoting factors such as VEGF and angiopoietin-1 and 2, promoting neovascularization around the tumour." (PMID 36678908, 2023). "Neutrophils are also responsible for releasing the factors of tumor-related angiogenesis, including vascular endothelial growth factor, fibroblast growth factor-2, and angiopoietin-1." (PMID 37444448, 2023). "Overexpression of Htatip2 in tumor cell lines has previously been shown to diminish expression of Angpt1 mRNA." (PMID 37847559, 2023). "Estrogen depletion induces BM niche cells to produce angiopoietin-2, which destabilizes the niche by interfering with angiopoietin-1/Tie2 signaling and promotes ER+ tumor cell survival via integrin β1." (PMID 37296983, 2023). "Herein, we suggested a positive correlation between the expression of angiopoietin-1 (Ang1) in the hepatocytes and the presence of neutrophils in vessel co-opting tumours." (PMID 36330498, 2022). "Generally, it is agreed that HIF-1A is involved which modulates the expression of VEGF-A, and angiopoietin-1, thus increasing tumour angiogenesis, glycolysis and cellproliferation." (PMID 36612205, 2022). "The bone marrow niche cells produce angiopoietin-2 (ANGPT2), that destabilize the local endothelium by impairing ANGPT1/Tie2 signaling and promotion of tumor cell survival." (PMID 35150338, 2022). "By targeting ANGPT1, miR-375 suppresses proangiogenic activity and miR-3682-3p weakens angiogenesis both affecting tumor progression." (PMID 36300115, 2022). "Biomarker analysis in patients enrolled in the RESORCE trial has shown that plasma levels of angiopoietin 1, which promotes tumor proliferation and angiogenesis, are prognostic in patients treated with regorafenib but not in the overall population." (PMID 36551730, 2022). "We then stained rat pituitaries from wild‐type (WT) rats and MENX tumor‐bearing rats and confirmed that Angpt1 is downregulated whereas Angpt2 is upregulated in the tumors (Fig EV1)." (PMID 35266635, 2022). "Angiopoietin-1 (Ang1) is expressed by pericytes, fibroblasts, stromal cells and tumour cells and has anti-inflammatory effects, generates neovascularization and contributes to vascular homeostasis and protection." (PMID 35549955, 2022). "Neutrophils release the factors of tumour-related angiogenesis, such as vascular endothelial growth factor, angiopoietin-1 and fibroblast growth factor-2." (PMID 35743468, 2022). "Angiogenesis in hypervascular tumours such as HCC is partly regulated by angiopoietins especially the well-characterized angiopoietin-1 (Ang1) and angiopoietin-2 (Ang2) which bind to the tyrosine kinase receptor." (PMID 35203390, 2022). "Although NF‐PitNET cells express much higher levels of Angpt2 than Angpt1, ECs secrete Angpt1, which can also promote tumor‐bound Tie2 activation." (PMID 35266635, 2022). "This induced pro-angiogenic factor substitution via activation and/or upregulation of members of the fibroblast growth factor (FGF) family, notch signaling, ephrin, or angiopoietin-1 re-establishes tumor neovascularization, resulting in tumor relapse." (PMID 34041019, 2021).